NRP1 (neuropilin 1)
Diseases named in the same sentence as NRP1 in open-access papers (continued):
Sharing a sentence is not in itself a finding about the gene and the disease.
COVID-19 (continued). "In current analysis, NRP1 is a candidate therapeutic target for treating COVID-19 patients with LUSC." (PMID 34168096, 2021). "Involvement of NRP-1 in immune function is compelling, given the role of an exaggerated immune response in disease severity and deaths due to COVID-19." (PMID 33395426, 2021). "We found that SARS-CoV-2 entry factors, including ACE2, TMPRSS2, FURIN, and NRP1, have elevated expression in nasal squamous cells from male individuals with moderate and severe COVID-19." (PMID 34330889, 2021). "Drugs having a high affinity to CendR binding pocket of NRP1 can be used in the COVID-19 treatment by blocking SARS-CoV-2 entry into cells." (PMID 34803446, 2021). "Severe COVID-19 also causes arterial injury, with the resulting potential up-regulation of NRP-1 pointing to the possibility of targeting NRP-1 for treatment of COVID-19." (PMID 33395426, 2021). "We postulate that this myocardial fibrosis is likely to be a pre-existing risk factor for severe disease courses of COVID-19, whereby increased expression of sIL1-RL1 induces NRP-1 expression that facilitates ACE2-mediated SARS-CoV-2 entry into the lung." (PMID 34745111, 2021). "Pathological analysis of olfactory epithelium obtained from human COVID-19 autopsies revealed that SARS-CoV-2 infected NRP1-positive cells facing the nasal cavity." (PMID 33082293, 2020). "Conversely, transcript levels of the VEGF-A co-receptor NRP-1 were increased in COVID-19 patients compared to healthy controls." (PMID 32869019, 2020). "Cellular staining of NRP1 (IF, ab81321, n = 6) of post-mortem olfactory tissue sections showed high detection of NRP1 in infected epithelial cells of COVID-19 patients compared to control individuals (n = 7)." (PMID 33164751, 2020). "Next, we explored the role of NRP1 using SARS-CoV-2 isolated from COVID-19 patients from the Helsinki University Hospital." (PMID 33082293, 2020). "Statistical comparison using the Wilcoxon signed-rank test revealed a non-significant trend in the control group (p = 0.0625), and a significant difference in the COVID-19 group (p = 0.03125), indicating that NRP1 expression remains elevated relative to ACE2 even during infection." (PMID 40722799, 2025). "NRP1 expression in lymphocytes was not specific to COVID-19 but was also observed in influenza and noninfectious causes of death." (PMID 41159753, 2025). "Consequently, neuropilin-1 has assumed a significant role in COVID-19, prompting further investigation to understand its impact on the infectious mechanism of this disease." (PMID 39908250, 2025). "Intense NRP1 expression in alveolar macrophages was not specific to COVID-19 but was also noted in other causes of death (n = 28)." (PMID 41159753, 2025). "Nevertheless, normal weight individuals with previous obesity may have lower COVID-19 risk since present reduced ACE2 and NRP1 protein levels, receptors that bind directly to the SARS-CoV-2 virus." (PMID 40806445, 2025). "Further studies are therefore needed to help navigate such contradictory findings and to demonstrate whether the upregulation and participation of NRP-1 in COVID-19 could result in long-term complications." (PMID 39205219, 2024). "G4 on the NRP1 promoter could be a potentially valuable biomarker for predicting COVID-19 complications, and targeting G4 on the NRP1 promoter may yield favorable clinical outcomes in COVID-19 patients." (PMID 38674009, 2024). "The initial step of COVID-19 pathogenesis involves that the viral spike (S)-protein interacts and anchors to susceptible host tissue by hijacking of specific CSRs (i.e., ACE2 and NRP1)." (PMID 38555403, 2024). "These authors also reported upregulated NRP1 levels in β-cells from individuals with COVID-19." (PMID 39205219, 2024). "For example, “Describe the role of neuropilin-1 (NRP1) in COVID-19” is a summary question." (PMID 39180335, 2024).
COVID-19 (continued). "Severe COVID-19 infection also causes arterial damage, further increasing NRP-1 expression, a contention supported by observations of increased NRP-1 RNA in cells infected with SARS-CoV-2 isolated from bronchoalveolar lavage fluid from patients with COVID-19." (PMID 40008234, 2024). "In addition, neuropilin-1 seems to play an important role in mechanisms linking COVID-19 to diabetic nephropathy." (PMID 39228893, 2024). "All these results together provided new insights into the molecular mechanism of the G4 structure in the epigenetic regulation of NRP1 gene transcription, and they showed the potential clinical application of G4-based drugs for COVID-19 prevention and treatment." (PMID 38674009, 2024). "The frequent renal involvement with organ damage in patients with COVID-19 is undoubtedly multifactorial, but the expression on renal cells of the key receptors promoting SARS-CoV-2 entry, such as ACE2, TMPRSS2, and NRP1 can make the kidney particularly susceptible to SARS-CoV-2 infection." (PMID 38255667, 2023). "In this way, NRP1 facilitates COVID-19 cell entry and infectivity." (PMID 36631871, 2023). "Interestingly, we did observe that certain COVID-19-associated genes, including CTSL and NRP-1, were significantly downregulated specifically in the AD cells following infection." (PMID 38098019, 2023). "NRP1 assists the binding of the S protein to ACE2; viral replication in vitro is inhibited by anti-NRP1 antibodies, indicating that NRP1 may be an effective target in COVID-19 treatment." (PMID 37515185, 2023). "The high-affinity binding between the SARS-CoV-2 S-protein and NRP1 suggested that this binding might play a role in COVID-19 severity since their binding promotes SARS-CoV-2 invasion through NRP1." (PMID 38138098, 2023). "Apart from several neurological complications, the increased expression of NRP1, a cell surface receptor, in COVID-19 may lead to the progression of primary brain tumors." (PMID 37239234, 2023). "Similarly, in WikiPathway pathway analysis results, SARS-CoV-2 altering angiogenesis via NRP1 and Endochondral Ossification are involved in the progression of COVID-19 and OA, respectively." (PMID 37283761, 2023). "Despite subsequent studies identifying NRP1 and CD147 as additional host cell receptors for SARS-CoV-2 entry, few studies have investigated the effect of variants within these genes and COVID-19 severity." (PMID 37761938, 2023). "In addition, we showed that SNPs within ACE2, TMPRSS2, NRP1 and CD147 have variable associations with COVID-19 severity across these ethnic groups." (PMID 37761938, 2023). "Hence, the disturbance in the NRP-1/VEGF-A system by SARS-CoV-2 during long COVID-19 appears still uncertain." (PMID 36557705, 2022). "Besides, we found that NRP1 was significantly higher in lung tissues from COVID-19 patients than non-COVID-19 people at both bulk and single-cell level, which was consistent with previous studies." (PMID 36338984, 2022). "These TFs may be responsible for the dynamic NRP1 mRNA expression change in the lungs of severely ill COVID-19 patients." (PMID 35458567, 2022). "NRP-1 has an important role in the pathogenesis of COVID-19 and AIS, and could be the potential biomarker linking the development of AIS in COVID-19." (PMID 36009579, 2022). "In addition, the high NRP-1 serum level in COVID-19 reflects retinal injury due to the over-expression of NRP-1 receptors in retinal ganglion cells that provokes retinal micro-hemorrhages." (PMID 36009579, 2022). "It was reported that COVID-19 patients were characterized with changes in peripheral white blood cells and immune cells, so we also analyzed the protein concentration of NRP1 in plasma and compared it with that of ACE2 via HPA." (PMID 36338984, 2022). "Furthermore, in our investigation, there was a strong association between NRP-1 mRNA expressions and mediators of inflammation, such as NF-κB p50, NF-κB p65, PGE2, and TXA2 in COVID-19 patients." (PMID 36298501, 2022).
COVID-19 (continued). "In both severe and non-severe COVID-19 patients, NF-κB p50, NF-κB p65, and NRP-1 mRNA expression levels were linked with all cytokines." (PMID 36298501, 2022). "Therefore, the aim of the present study was to elucidate the potential role of NRP-1 in COVID-19 patients with AIS." (PMID 36009579, 2022). "Notably, whereas IL12RB1, NRP1 and NRP2 were only moderately increased as a function of viral load, CNTN1 expression was significantly correlated with viral load in these COVID-19 patients, an association that was more prominent in older patients." (PMID 35931765, 2022). "Recently, it was found that impairment of renal and cardiac function biomarkers in serum might be the result of a cytokine storm and an increase in the expression of ACE-2 and NRP-1 in COVID-19 patients." (PMID 36298501, 2022). "SARS-CoV-2 may transmit to the brain through NRP-1 in the olfactory epithelium of the nasal cavity, leading to different neurological disorders, and therefore about 45% of COVID-19 patients had neurological manifestations." (PMID 36009579, 2022). "In addition, significant upregulation of NRP-1 was found in biological samples from COVID-19 patients compared to healthy controls." (PMID 35002503, 2022). "With the direct activation of AP-1 (c-Jun and c-Fos) in NRP1–CTSL pairs, monocyte/macrophage cells may be more susceptible to SARS-CoV-2 infection in COVID-19 patients compared to healthy donors." (PMID 35458567, 2022). "Most studies suggest that high NRP-1 serum is linked with COVID-19 and AIS severities, but have not explained the underlying molecular mechanisms." (PMID 36009579, 2022). "According to the theoretical basis and the enrichment results that tuftsin could target ACE2 and NRP1 in the COVID-19 pathway, the possible interactions of tuftsin with the two SARS-CoV-2 entry receptors were determined by molecular docking analyses." (PMID 35402510, 2022). "Very limited evidence links long COVID-19 to dysregulation of the NRP-1/VEGF-A pathway." (PMID 36557705, 2022). "It has been demonstrated that NRP-1 upregulates Treg cells, so may reduce exaggerated immune response-induced COVID-19 severity." (PMID 36009579, 2022). "Impairment of renal and cardiac function biomarkers in serum might be the result of a cytokine storm and an increase in the expression of ACE-2 and NRP-1 in COVID-19 patients." (PMID 35891209, 2022). "Furthermore, NRP1 is involved in immune function, thus its role in the exaggerated immune response in severe COVID-19 cases has also been proposed." (PMID 35215277, 2022). "Therefore, the aim of the present study was to clarify the potential role of NRP-1 in COVID-19 patients with AIS." (PMID 36009579, 2022). "Evidence suggests that the NRP-1/VEGF-A pathway may participate in the pathogenesis of viral diseases other than COVID-19." (PMID 36557705, 2022). "As NRP1 also plays an important role in immunity, cancer pathogenesis, and infection of SRAS-CoV-2, it is meaningful to explore the expression of NRP1 in different normal and cancer tissues to predict the susceptibility to COVID-19." (PMID 36338984, 2022). "It is worth noting that NRP1 had been reported to be ubiquitously expressed in the brain regions, especially in hippocampal formation and showed an elevated expression in the infected olfactory epithelial cells isolated from human COVID-19 autopsies." (PMID 35377064, 2022). "Taking these into account, we wondered whether antibody cocktails targeting NRP1 could benefit COVID-19 patients, especially patients complicated with cancer." (PMID 36338984, 2022). "However, further research is needed to refine the current understanding of the potential role of NRP1 in diabetic nephropathy, particularly in conjunction with COVID-19." (PMID 35955539, 2022). "Furthermore, VEGF, which is an agonist of the NRP-1 receptor, is elevated in COVID-19 due to the blocking of VEGF/NRP-1 signaling by the spike protein of SARS-CoV-2, with subsequent development of neuropathic pain." (PMID 36009579, 2022).
COVID-19 (continued). "Besides, the role NRP1 plays in the immunity microenvironment also needs exploration to better understand the pathogenesis of COVID-19." (PMID 36338984, 2022). "Furthermore, ACE-2 mRNA and NRP-1 mRNA expression levels demonstrated a significant increase in both severe and moderate COVID-19 patient groups." (PMID 35891209, 2022). "Our study concluded that impaired renal and cardiac biomarkers might be attributed to increased expression levels of TLR2, TLR4, ACE2, and NRP-1 mRNA in both moderate and severe COVID-19 patients." (PMID 35891270, 2022). "The likelihood of usage of NRP-1 may be substantiated by the report of COVID-19 patients showing upregulation of the receptor in lung samples." (PMID 34572076, 2021). "Taken altogether, NRP1 might be a potential target for comorbidity of COVID-19 and lung cancer, although further experimental validation is lacking." (PMID 34168096, 2021). "Similarly, other authors used antibodies against the spike protein to demonstrate a markedly elevated expression of NRP-1 in infected olfactory epithelial cells from human COVID-19 autopsies." (PMID 34202613, 2021). "Cantuti-Castelvetri and colleagues also analyzed NRP-1 protein expression using the Human Protein Atlas, revealing high NRP-1 expression in the epithelial surface layer of the respiratory and gastrointestinal tracts, both of which are known to be affected by COVID-19." (PMID 33395426, 2021). "Moreover, a higher NRP-1 expression was observed in pancreatic β cells compared with α cells in both non-COVID-19 subjects and COVID-19 patients." (PMID 35053020, 2021). "The multifaceted role of NRP-1 in the immune system has made it an attractive potential target for immunotherapies such as monoclonal antibodies for use against autoimmune conditions, tumors, and perhaps infectious diseases like COVID-19." (PMID 33395426, 2021). "Dorsal root ganglia are reported to express ACE2, furin, and NRP1, the complete receptor machinery for SASR-CoV-2 infection." (PMID 34961486, 2021). "So targeting the host factor NRP1 in COVID-19 patients with LUSC may suppress both the transmission of NRP1 and the tumor development." (PMID 34168096, 2021). "What is unknown at this time is whether the involvement and up-regulation of NRP-1 in COVID-19 may translate into long-term consequences with impaired angiogenesis and/or immune functions." (PMID 33395426, 2021). "In addition, a large number of COVID-19-associated genes are coexpressed with the genes positively correlated with ACE2 and NRP1 in renal carcinomas." (PMID 34698182, 2021). "Therefore, the authors suppose that NRP-1 is a mediator for several retinal findings in patients with COVID-19." (PMID 34202613, 2021). "On this premise, the identification of NRP1 as another cellular mediator which may promote the entry of SARS-CoV-2 into host cells offers a potential novel therapeutic antiviral target against COVID-19." (PMID 33462185, 2021). "NRP-1 is implicated in several aspects of a SARS-CoV-2 infection, including possible spread through the olfactory bulb and into the central nervous system and increased NRP-1 RNA expression in lungs of severe COVID-19." (PMID 34209289, 2021). "It remains to be seen whether blocking the interaction between SARS-CoV-2 and NRP-1 could be an effective therapy in the fight against COVID-19." (PMID 33395426, 2021). "It is also unknown whether the NRP1 up-regulation and involvement in COVID-19 may have direct implications for the disease’s outcomes and long-term consequences, including possible immune dysfunction." (PMID 34360529, 2021). "Interestingly, except for FURIN, the expression level of ACE2, TMPRSS2, and NRP1 were significantly dysregulated in nasal tissues from COVID-19 positive patients." (PMID 33732102, 2021).
COVID-19 (continued). "Since RAS-related proteins, NRP1 and VEGF, are implicated in COVID-19 severity, we hypothesized that increased risk of severe COVID-19 in PCOS may be reflected in altered soluble NRP1 (sNRP1) levels and their association with RAS-related proteins and VEGF." (PMID 33521617, 2021). "Moreover, the abundance of NRP1 in COVID-19 patients makes it feasible to target NRP1 and get response in patients." (PMID 34168096, 2021). "It is unknown whether involvement and up-regulation of NRP-1 in COVID-19 may translate into disease outcome and long-term consequences, including possible immune dysfunction." (PMID 33395426, 2021). "Nevertheless, it is likely that Neuropilin-1 could be also involved in the cytokine storm and the subsequent hyper-inflammatory state observed in COVID-19 patients, although further dedicated studies in this sense are necessary." (PMID 33540664, 2021). "Furthermore, COVID-19 has been associated with a wide spectrum of neurological symptoms and Neuropilin-1 has been proposed as a key factor in the neurological manifestation of COVID-19 by enhancing the entry of SARS-CoV-2 into the brain." (PMID 33540664, 2021). "Incidentally, endothelial and respiratory epithelial cells express the highest level of NRP1 in the body, which may explain the excessive damage exerted upon lung and myocardial tissue particularly in COVID-19 patients." (PMID 34025658, 2021). "Importantly, recent ‘omic’ analyses revealed a significant upregulation of NRP-1 in biological samples from COVID-19 patients compared to healthy controls." (PMID 34961486, 2021). "We anticipate that widespread expression, abundance in the respiratory and olfactory epithelium, and the functionalities of NRP-1 factor into the multiple systemic effects of COVID-19 and challenges we face in management of disease and potential long-term sequelae." (PMID 33395426, 2021). "In this study, molecular characterization via high-throughput analysis and biochemical assays reveals that NRP1 is highly expressed in AD, which suggests that NRP1 may be a potential genetic therapy target in AD patients with COVID-19." (PMID 34745215, 2021). "Additionally, some neuropathological analysis from COVID-19 patients revealed that the SARS-CoV-2 infected Neuropilin 1 (NRP-1) positive cells in olfactory epithelium and bulb, as spike proteins were detected in those cells." (PMID 32764275, 2020). "Importantly, ‘omic’ analyses revealed a significant upregulation of NRP-1 in biological samples from COVID-19 patients compared to healthy controls." (PMID 32869019, 2020). "Based on the expression of neuropilin-1 in endothelial and epithelial cells of the olfactory and respiratory system, its upregulation in SARS-CoV-2-infected blood vessels of COVID-19 patients was associated with vascular endothelialitis, angiogenesis, and thrombosis." (PMID 33392206, 2020). "NRP1 may also play a role in SARS-CoV-2-induced lesions in retinal cells associated with the VEGF-A factor, triggering microhemorrhages and hyperreflective lesions in the retina of COVID-19 patients." (PMID 40431631, 2025). "NRP1 catalyzes proteolytic cleavage, aiding viral fusion with the cellular membrane and entry into target cells so NRP1 could be a strong candidate against COVID-19." (PMID 39908250, 2025). "Overall, this study provides the first important evidence for SARS-CoV-2 infection mediated by NRP1 in BMMs for the first time and establishes a potential relationship between osteoclast differentiation disorder and skeletal system metabolism disorder in COVID-19 patients." (PMID 37645223, 2023). "NRP1 is involved in angiogenesis, which may explain the increased incidence of long-term neurological complications and the progression of primary brain tumors in COVID-19 patients." (PMID 37239234, 2023).